CD163 (CD163 molecule)
Diseases named in the same sentence as CD163 in open-access papers (continued):
Sharing a sentence is not in itself a finding about the gene and the disease.
melanoma (continued). "Single-cell analysis showed that individual melanoma TAMs expressed different levels of multiple markers associated with M2-like states, like Arg1, CD206 and CD163, usually co-expressed, but also defining individual subsets." (PMID 34572807, 2021). "Together, these data suggest that factors controlling homing and retention of CD163+ macrophages in melanoma differ from those governing infiltration of lymphocytes." (PMID 34454518, 2021). "We observed that CD163+ve TAMs were higher in thicker pT4 melanomas than those found in dermal nevi." (PMID 34831352, 2021). "A dense CD163+ve MΦ infiltration in melanoma stromal tissue and CD68+ve MΦ infiltration at the invasive front were associated with poor overall survival." (PMID 34831352, 2021). "In fact, and at the protein level, FRβ expression was observed in CD163+ cells in melanoma and in areas enriched in CD68+ cells in colon adenocarcinoma." (PMID 32532019, 2020). "High co-expression of CD163 and LAG-3 was associated with poor clinicopathological indexes of melanoma and worse survival compared to the high expression of the single markers." (PMID 32756500, 2020). "In the context of melanoma, it was reported that CD163-positive TAMs can suppress antitumor immunity in anti-PD-1-resistant melanoma." (PMID 32756500, 2020). "In metastases from melanoma patients, high levels of miR-146a, miR-155, miR-125b, miR-100, let7e, miR-125a, miR-146b, and miR-99b were detected and correlated with CD163, CD14, CD209, CD68, ITGAM, and CD33 myeloid markers." (PMID 32793228, 2020). "Doxorubicin-loaded stealth liposomes coated with an anti-CD163 monoclonal antibody have shown promising results regarding tumor regression in mouse models of PD-1 therapy resistant melanomas and metastatic ovarian cancer." (PMID 32752088, 2020). "A recent study demonstrated that the specific targeting of a subset of M2-TAMs expressing CD163 induced tumor regression in a murine melanoma model (C57BL/6J mice subcutaneously injected with the anti-PD-1 resistant YUMM1.7 cell line)." (PMID 33212945, 2020). "In the present study, we found two notable results; first, PD-1 and LAG-3 correlated with the CD163 expression, suggested as a poor prognostic factor in melanoma." (PMID 32756500, 2020). "CD163+ TAMs represent a pro-tumorigenic fraction of TAMs that possess immunosuppressive characteristics in the melanoma mouse model." (PMID 32752088, 2020). "Here, we evaluate the presence of CD68+ and CD163+ macrophages in FFPE human primary melanoma lesions and determine their correlation with the functional canonical M1:M2 enzymes inducible nitric oxide synthase (iNOS) and arginase." (PMID 32843682, 2020). "Melanoma-patient-derived sera induced higher levels of CD163+CD206+ macrophages compared to healthy-donor-derived sera, while HLA-DR and CD86 expression remained unchanged." (PMID 30712866, 2019). "The stromal expression of periostin was upregulated in inflamed skin, and significantly more CD163+ M2 macrophages were recruited to the melanomas in inflamed skin." (PMID 30621220, 2019). "This led us to investigate if periostin and CD163+ M2 macrophage infiltration were prognostic factors in human melanoma." (PMID 30621220, 2019). "With the help of this antibody, P2Y12 expression was confirmed on CD68+ CD163+ TAM of melanoma in situ." (PMID 31591378, 2019). "We recently reported that a subset of mature CD163+ TAM present in mouse melanomas, exhibit transcripts related to T cell immune suppression." (PMID 31766350, 2019). "A significantly higher number of CD163+ M2 macrophages also infiltrated into the melanomas in the inflamed mice than that in the control mice." (PMID 30621220, 2019). "This is in-line with our finding that melanoma-conditioned TAMs displayed M2-like phenotype, including increased CD163 protein expression and TNF-α low, IL-1β low, TGF-β high and IL-10 high phenotype." (PMID 30459241, 2018).
melanoma (continued). "Consistent with these backgrounds, we found that high expression of IL-34 in refractory metastatic melanoma correlates positively with increased frequencies of CD163+ (a marker for M2-polarization) macrophages compared to primary melanoma." (PMID 29515691, 2018). "More than 10% of CD163+ histiocytes were observed at advancing tumour edges in 68.1% of primary melanomas and 53.8% of metastases." (PMID 29973670, 2018). "Multispectral fluorescent immunohistochemistry with a panel including CD3, CD8, FoxP3, CD163, PD-L1 was used to analyze the tumor microenvironment in 17 patients with melanoma among our 36-patient cohort to predict successful TIL generation." (PMID 26500776, 2015). "This may be MAPK-driven, as increasing accumulation of CD68+ and CD163+ microglia is similarly observed in melanoma, correlating with greater tumour size and Breslow depth, and at significantly higher levels in BRAF-altered samples." (PMID 39948623, 2025). "CD163+ TAMs in the melanoma TME showed highly variable levels of HLA-DR expression." (PMID 38903497, 2024). "We found that a subset of CD163+ TAMs in metastatic melanoma co-expressed the cell proliferation marker Ki-67, indicating these TAMs indeed proliferate within the melanoma TME." (PMID 38903497, 2024). "Interestingly, emactuzumab, an anti-human CD115 mAb, reduced the number of CD163 + CD206 + M2 macrophages in melanoma patients by depleting immature TAMs before the IL-4-stimulated phase." (PMID 39003350, 2024). "CD163+ TAMs in the melanoma TME displayed molecular features suggesting their monocytic origin." (PMID 38903497, 2024). "In the melanoma samples we examined, numerous CD163+ TAMs co-expressed PD-L1." (PMID 38903497, 2024). "We therefore speculate that M-CSF-driven proliferation of CD163+ TAMs may be potentiated by T cell attack on melanoma cells, leading to increased expression of PD-L1, PD-L2 and other immune-suppressive molecules in the TME." (PMID 38903497, 2024). "POSTN causes the stimulation of CD163 + macrophages to produce several cytokines including Treg-associated chemokines [chemokine ligand 17 (CCL17), CCL22] which in turn induce the recruitment of Tregs to the tumor site in melanoma." (PMID 39003350, 2024). "Notably, emactuzumab, an anti-human CD115 Ab, reduced CD163+ CD206+ M2 macrophages in melanoma cases by eliminating immature TAMs before being stimulated by IL-4." (PMID 37525217, 2023). "Notably, in our present study, IL-23p19 was increased in both melanoma cells and CD163+ M2 macrophages." (PMID 36980564, 2023). "Tissue from a patient with Nivolumab-resistant metastatic melanoma showed a remarkable increase in expression of IL-34 compared with primary site melanoma tissues, and this upsurge in expression was demonstrated to be connected with greater frequencies of CD163, an M2 macrophage marker." (PMID 36798830, 2023). "The high transcriptional IL4I1 expression by MHCII+ CD163− TAMs in MeLiM pigs with regressing melanoma was unexpected, but may result from the enriched IFNγ, TNFα, IL12 and IL6 tumor microenvironment between R0 and R1 stages." (PMID 37526660, 2023). "Moreover, mRNA expression and protein production of these pro-angiogenetic factors was increased in A375 melanoma cells as well as CD163+ M2 macrophages by the stimulation of LL-37 in vitro." (PMID 36980564, 2023). "In particular, the appropriate activation of MHCII+ CD163− TAMs might lead to more efficient treatment for melanoma." (PMID 37526660, 2023). "Additionally, CSF1 expression correlates with accumulation of CD8+ T cells and CD163+ TAMs in melanoma, and anti−PD1 and anti−CSF1R combination therapy induced regression of melanoma in preclinical studies." (PMID 35664746, 2022). "In melanoma, the presence of CD163+/PD-L1+ TAMs led to a favorable ICI response." (PMID 36362023, 2022).
melanoma (continued). "Blocking PD1/PD‐L1 signaling in CD163+ TAMs with antibodies could induce M1‐like polarization and increase macrophage phagocytosis, reduce tumor burden and prolong survival, and result in an increased release of sCD163 in the lesional skin of melanoma." (PMID 33463063, 2021). "Finally, in tumor specimens from patients with melanoma, high bcl-2 expression correlated with increased infiltration of M2-polarized CD163+ macrophages, hence supporting the clinical relevance of the crosstalk between tumor cells and microenvironment." (PMID 32269145, 2020). "Finally, in tumor specimens from patients with melanoma, high bcl-2 expression correlated with increased infiltration of M2-polarized CD163+ TAM, hence supporting the clinical relevance of tumor/microenvironment crosstalk." (PMID 32269145, 2020). "Moreover, they express higher levels of TAM-related markers (CD206, MerTK and CD163), compared to blood circulating CD14+ DCs, we previously linked to lower immunological response to DC-based vaccines in melanoma patients." (PMID 32488012, 2020). "In this study, 46.1% of melanoma specimens showed high expression of CD163." (PMID 32756500, 2020). "In addition, a larger number of CD163+ M2 macrophages infiltrated into thick melanomas than into the thin ones." (PMID 30621220, 2019). "The melanomas in the inflamed skin harbored more CD163+ M2 macrophages." (PMID 30621220, 2019). "However, our data further support the implication of CD163+ cells in dominant inhibitory pathways in melanoma, implying that the presence of protumor and immunosuppressive myeloid cells as shutting down their function in TME ultimately favors tumor outgrowth." (PMID 31730502, 2019). "However, no studies have comprehensively investigated the relationships between periostin and CD163+ M2 macrophages regarding the progression and prognosis in patients with melanoma." (PMID 30621220, 2019). "Targeted-depletion of this minor CD163+ TAM subset enhanced melanoma-infiltration by CD8 T cells and promoted CD8 T cell-mediated tumor regression in mice; this was also accompanied by the recruitment of fresh monocytes and immature macrophages with an immune stimulatory phenotype." (PMID 31766350, 2019). "We detected P2Y12 in CD68+ CD163+ TAM of primary melanoma as well as melanoma metastases." (PMID 31591378, 2019). "Here we show that P2Y12 is expressed on CD163+ TAM of human melanoma in situ." (PMID 31591378, 2019). "Immunohistochemistry staining of melanoma tissues showed an enhanced expression of IL-34 in metastatic refractory melanoma compared to primary melanoma tissues, which correlates with increased frequencies of CD163+ macrophages." (PMID 29515691, 2018). "Tumor areas were objectively judged by two independent researchers at 600× magnification for each section, and quantification of IL-34, melanoma antigens or CD163 immunoreactivity on the randomly-selected more than 20 tumor areas in each section was measured using FV1000 OLYMPUS software." (PMID 29515691, 2018). "Interestingly, the antihuman CD115 Ab, emactuzumab, decreased the number of CD163+ CD206+ M2 macrophages in patients with melanoma by depleting immature TAMs before the IL-4 stimulation phase." (PMID 29410946, 2018). "Notably, immunofluorescence staining revealed that CD163+ macrophages were distributed in POSTN-expressing areas, suggesting that POSTN in melanoma can stimulate CD163+ macrophages to produce CXCL5." (PMID 29643991, 2018). "Melanoma resection species were obtained from a patient who developed a refractory melanoma against immunotherapy with Nivolumab, and stained with anti-IL-34, anti-melanoma antigens and anti-CD163 antibody." (PMID 29515691, 2018). "Similarly, PD-L1 expression was observed to positively correlate with the amount of CD163+ TAMs in melanoma." (PMID 29190964, 2017).
melanoma (continued). "In further support for a potential role of TAMs and IL-10 in melanoma is the presence of IL-10-producing TAMs in human melanoma metastases as revealed by the presence of CD163+ IL-10+ cells infiltrating human metastases in areas with high cytoplasmic HMGB1 expression." (PMID 27426915, 2016). "Herein, the decrease of these CD163+ TAMs noticed within melanomas could be involved to limit the endothelial cell recruitment through decreased growth factors excretion, and finally explain the increase in tumor necrosis as observed under Phenacetinum 4CH treatment." (PMID 33747916, 2021). "Analysis of the spatially constrained distribution of CD8+ and CD163+ cells, representative of the opposite circuits of antitumor vs protumor immunity, respectively, may assist in identifying melanoma patients with improved response and better outcome upon treatment with MAPK inhibitors." (PMID 31730502, 2019). "Corroborating the idea of worse prognoses of M2-infiltrating TAMs a study evaluating the correlation between CD163+ macrophages and survival rates in melanomas showed that lesions presenting a high population of CD163+ macrophages have significantly poor overall and melanoma-specific survival." (PMID 28074082, 2016). "The melanomas with brain metastases (BM) showed higher expression of CTLA-4, and lower expression of 4-1BB, CD163, GITR, IDO1, PR, EPCAM and ER-alpha than the melanomas without metastases." (PMID 40621453, 2025). "Highly multiplexed imaging of human melanoma shows similar major histocompatibility complex (MHC)-high CRATERs, which preferentially harbor CD8+ T cells as well as PD-L1+ and CD163+ dendritic cells (DCs)." (PMID 41109214, 2025). "Studies have shown that invasive melanomas have a greater quantity of CD68+ and CD163+ TAMs in comparison to benign nevi." (PMID 39703508, 2024). "These macrophage–tumor cell hybrids express M2-like macrophage markers (CD163, CD204, and CD206) and epithelial markers (cytokeratins and EpCAM) and are found in the peripheral blood of patients with PDAC, melanoma, and breast, ovarian, and colorectal cancer." (PMID 39516356, 2024). "An earlier report noted the correlation between CD163 and COX2 in melanoma, and we indeed confirmed the COX-2 expression in a subset of CD163+ TAMs." (PMID 38903497, 2024). "TAMs in melanoma are a diverse and constantly changing group, with a subset of unpolarized CD68+/CD163–/iNOS– macrophages consistently existing." (PMID 39703508, 2024). "Our data from the spatial analysis showed that immunosuppressive markers like CD163, CD209, and PDL1 were upregulated in the SLN (+) and SLN (−) of melanoma patients, which were mostly expressed on myeloid cells." (PMID 39062552, 2024). "We detected a decrease in the combined CD163 and CD206 expression in the macrophages treated with EVs from CD36-siRNA-transfected melanoma cells compared to EVs from NTC-transfected melanoma cells." (PMID 39062552, 2024). "We postulate that the classical CD16− monocytes are recruited into the melanoma TME, likely via tumour-derived CCL2, where they upregulate CD163 and gradually lose the expression of CD14 and CCR2." (PMID 38903497, 2024). "When we probed for M-CSF transcripts in melanoma tissue, we found these are abundantly available in the melanoma TME, often in close proximity to CD163+ TAMs." (PMID 38903497, 2024). "GrB+ lymphocytes associated positively with PD-L1+ tumor and stromal immune cells (p-values 0.009 and 0.027, respectively), IDO+ melanoma cells (p < 0.001), and tumor nest CD68+ and CD163+ macrophages (p-values 0.002 and 0.003, respectively) (data not shown)." (PMID 36551965, 2022). "For example, the increased stromal expression of periostin was significantly correlated with increased numbers of CD163+ TAMs in inflamed melanoma skin, suggesting that TAMs stimulated by POSTN play a significant role in the development of melanoma." (PMID 35409404, 2022).
melanoma (continued). "Previously documented markers including FOXP3 (Tregs), CD163 (TAMs), CD33 (TANs), FAP (CAFs), MIA (melanoma), and ALDH1A1 (HNSC), were used for cell-type annotation." (PMID 35812726, 2022). "Appealing studies have used anti-CD163 antibodies to target TAMs by decorating DOX-carrying liposomes with anti-CD163, to deplete TAMs and potentiate ICIs in melanoma." (PMID 36923553, 2022). "We compared their characteristics to the melanoma TAMs, evaluating the expression of CD11b, F4/80, Ly6C, CSF1R, iNOS, CD40, CD86, MHCII, Arg1, CD163 and CD206 expression by flow cytometry." (PMID 34572807, 2021). "In melanoma patients, adding bevacizumab to ipilimumab determined an augmented rate of CD8+ T cells and CD163+ dendritic macrophages, both on tumor tissue and in peripheral blood samples." (PMID 34123809, 2021). "Interestingly, immunostaining of melanoma samples from a patient who developed resistance to nivolumab revealed higher expression of IL-34, compared to the primary tumor, which positively correlated with an increased frequency of CD163+ TAMs and poor prognosis." (PMID 33212945, 2020). "Concurrent high expression of both CD163 and PD-1 (CD163highPD-1high) or LAG-3 (CD163highLAG-3high) in melanoma were independent poor prognostic factors." (PMID 32756500, 2020). "Primary untreated melanoma lesions were stained with CD68 and CD163 antibodies to identify macrophage populations, and the number of positive cells per mm2 was measured in both intratumoural tissue and peritumoural tissue." (PMID 32843682, 2020). "Fifty-seven formalin-fixed, paraffin-embedded primary melanomas were analysed by immunohistochemical analysis of CD68, CD163, inducible nitric oxide synthase (iNOS) and arginase expression." (PMID 32843682, 2020). "Melanoma cells isolated from the IF of A375M2 tumors were more secretory and induced CD163+CD206+ macrophages more efficiently ex vivo when compared to their TB counterparts." (PMID 30712866, 2019). "Agreement between primary melanoma and metastases was poor for total tumour-area PD-L1 expression, TIL assessment and CD163+ histiocytes at advancing tumour edge." (PMID 29973670, 2018). "We found a higher percentage of CD163+ TAMs than of CD68+ TAMs in both thymoma and thymic carcinoma samples, which was consistent with previous observations in Hodgkin’s lymphoma, malignant melanomas, and leiomyosarcomas." (PMID 25499804, 2014). "Moreover, CD163+/CD11c+ DCs within CRATERs presented a statistically significant increase in HLA-A and HLA-DPB1 levels, corresponding to MHC class II, and MART-1 melanoma antigen, compared with elsewhere in the tumor." (PMID 41109214, 2025). "Similarly, significant upregulation of CD163 and EGR2 highlights the polarised state of macrophages towards an M2 phenotype in melanoma samples." (PMID 40134439, 2025). "Despite their potential roles in tumour progression, the origin of CD163+ TAMs in human melanoma has not been thoroughly investigated." (PMID 38903497, 2024). "In the LN metastasis samples we examined, positive COX-2 expression was observed in a subset of the CD163+ TAMs, while the expression was often absent in the neighbouring melanoma cells." (PMID 38903497, 2024). "recently identified in a melanoma mouse model four different TAM subsets depending on their expression of the scavenger receptor CD163 and MHCII (CD163− MHCII−, CD163− MHCII+, CD163+ MHCII−, CD163+ MHCII+)." (PMID 37526660, 2023). "Use of this platform facilitated the robust assessment of the intensity of in situ PD-1 and PD-L1 expression on different cell types within the melanoma TME, with 41 combinations of expression patterns identified using six markers (PD-1, PD-L1, CD8, FoxP3, CD163, and Sox10/S100)." (PMID 35672823, 2022). "A dense intratumoral infiltration of both CD68+ve and CD163+ve TAMs has been reported in deeply-invasive malignant and metastatic melanomas compared to non-metastatic melanomas, and in malignant compared to benign melanocytic lesions." (PMID 34831352, 2021).